PRB3 (proline rich protein BstNI subfamily 3)
Description:
Acts as a receptor for the Gram-negative bacterium F.nucleatum.
Synonyms: PRG; G1
Tractability: Antibody: UniProt places it where antibodies can reach, with medium confidence; UniProt predicts a signal peptide or a membrane-spanning region; its Gene Ontology location is reachable by antibodies, with medium confidence.
Gene: Protein-coding gene on chromosome 12 (11,265,914 to 11,269,707, reverse strand). Ensembl gene ENSG00000197870.
Subcellular location: Secreted
Gene Ontology:
Molecular function: protein binding
Biological process: defense response to Gram-negative bacterium
Cellular component: extracellular region
Genetic constraint (gnomAD): Loss-of-function variants: 9 observed, 8.63 expected, observed/expected ratio (o/e) 1.04, 90% interval 0.62 to 1.73. That is too few expected variants to judge how well the gene tolerates losing a copy. Missense variants: 277 observed, 311.69 expected, observed/expected ratio (o/e) 0.89, 90% interval 0.81 to 0.98. Synonymous variants: 87 observed, 110.21 expected, observed/expected ratio (o/e) 0.79, 90% interval 0.66 to 0.94.
Homologues: Paralogues in human: PRB2 (75% identical), PRB4 (58% identical), PRB1 (43% identical), PRH1 (33% identical), PRH2 (30% identical), PRR4 (15% identical).
Diseases named in the same sentence as PRB3 in open-access papers:
PRB3 is named in the same sentence as 5 diseases in open-access papers, as found by Europe PMC text mining. Sharing a sentence is not in itself a finding about the gene and the disease. The quoted sentences say what the papers report.
prolactinomas (1 paper, 2025). "Additionally, molecular markers including DRD2 gene variants, altered expression levels of PRDM2, Filamin A, or PRB3, and dysregulated TGF-β1/Smad3 signaling pathways offer insights into the molecular pathogenesis of aggressive prolactinomas." (PMID 41013821, 2025).
salivary gland acinic cell carcinoma (1 paper, 2021). A carcinoma of the salivary gland characterized by serous acinar cell differentiation. "Low expression of PRB3 was found to be associated with tumor recurrence in prolactinomas and salivary gland acinic cell carcinoma." (PMID 33885377, 2021).
tumor (3 papers, 2014 to 2024). "Additionally, reduced PRB3 expression was associated with tumor recurrence, suggesting that low PRB3 mRNA levels may contribute to dopamine agonist resistance and tumor recurrence in prolactinomas." (PMID 39830981, 2024).
cancer (1 paper, 2017). A tumor composed of atypical neoplastic, often pleomorphic cells that invade other tissues. "The rearrangement results in the promoter of another highly-expressed salivary gland gene, PRB3, possibly driving overexpression of ZNF217, a reported oncoprotein in several cancer types." (PMID 28212443, 2017).
PRB3 also shares sentences with these, for which no sentence is quoted: pituitary adenomas (1 paper).